IFNG (interferon gamma)
Diseases named in the same sentence as IFNG in open-access papers (continued):
Sharing a sentence is not in itself a finding about the gene and the disease.
tumor (continued). "During the early stages of tumor growth, Jaml−/− mice had fewer numbers of IFNγ-producing γδ tumor-infiltrating lymphocytes (TIL) demonstrating that the γδ T cell response to B16 tumor growth is mediated, at least in part, by JAML-CXADR interactions." (PMID 35480230, 2022). "To measure the acute response of the signal transduction, we treated the tumour cells with a titration of IFNγ and harvested the cellular lysates for analysis at 2 h post-stimulation." (PMID 35982220, 2022). "T-bet expression is crucial for TH1 differentiation and IFNγ production, which are important for orchestrating tumour-specific immune responses." (PMID 35158816, 2022). "In particular, interferon gamma (IFN-γ) and granzyme B are known to increase tumor immunogenicity, inhibit tumor cell proliferation, and enhance the cytotoxic function of natural killer (NK) cells and cytotoxic T lymphocytes (CTLs)." (PMID 36230744, 2022). "One sample from IFNγ group had only a small focus of micrometastasis, but also a well-circumscribed tumor nodule in the spleen, in contrast to the other mice that had diffuse infiltration of the spleen by tumor." (PMID 35459800, 2022). "IFNγ strongly stimulates PD-L1 expression in the tumor microenvironment, thereby hampering antitumor immunity and ICB therapy." (PMID 34385592, 2022). "In tumors, IFNγ secreted by activated tumor-infiltrating T cells can induce the expression of the MHC-I component genes in cancer cells, boosting the tumor antigen presentation and enhancing the CD8+ T-cell-mediated cancer cell clearance." (PMID 36551849, 2022). "Due to the high migratory and tumor-homing abilities of Tie2-expressing monocytes, the cell-specific expression of IFNγ in Tie2+ monocytes allowed the targeted release of IFNγ at the tumor sites." (PMID 36679900, 2022). "IFNγ can promote anti-tumor activity indirectly, by inducing secretion of lymphocyte-attracting chemokines such as CXCL9, CXCL10 and CXCL11, and by skewing the attracted immune infiltrate to be more inflammatory." (PMID 35395848, 2022). "Later on, the pivotal role of the interferon-γ (IFNγ) was proven to explain the anti-tumor and anti-bacterial abilities of these cells, via the production of reactive oxygen species (ROS)." (PMID 35163420, 2022). "IL-15 (activates lymphocytes to produce IFNγ) binds to the IL-2 receptor and stimulates both antigen-independent expansion and the long-term survival of anti-tumor CD8+ T cells." (PMID 36142615, 2022). "In line with this, Hollenbaugh and colleagues showed that the ability of host immune cells to respond to the T-cell-derived IFNγ was crucial to inducing acute tumor rejection after adoptive T-cell transfer in the EG7 tumor model." (PMID 35884605, 2022). "Increased IFNγ production by Teffs results in increased production of PD-L1 in both cancer cells and immune cells to hinder anti-tumor responses." (PMID 36142818, 2022). "In the spontaneous TRAMP model, iNKT cells infiltrate prostate tumor via CCL2/CCR5 pathway; however, tumor cells only partially activate iNKT cells, because of their impairment to release IFNγ." (PMID 36338516, 2022). "Other studies also have documented the importance of IFNγ in the CTLA-4 blockade-mediated anti-tumor response." (PMID 35392976, 2022). "For example, a TGGA analysis of laryngeal cancer revealed that CDKN2A has the highest mutation frequency among the top significant differential genes that IFNG significantly correlated with tumor stage and the degree of tumor differentiation." (PMID 36009223, 2022). "Deletion of TC-PTP enables spontaneous and implanted tumor rejection via a combined effect on T-cell signaling and interferon gamma (IFN-γ)–induced JAK–STAT signaling in the tumor." (PMID 36328244, 2022). "Compared with XH administration, PX exhibited a stronger antitumor effect, such as smaller tumor volume, lower interleukin 17 (IL-17), IL-6 and tumor necrosis factor-alpha (TNFα) serum levels, and higher interferon-gamma (IFN-γ) concentration." (PMID 36582768, 2022).
tumor (continued). "In contrast, IFNγ can prevent tumor progression by inhibiting the tumor cell cycle and induction of apoptosis and necroptosis." (PMID 36544523, 2022). "Conversely, STUB1 inactivation amplifies IFNγ signaling, sensitizing tumor cells to cytotoxic T cells in vitro." (PMID 35395848, 2022). "Low concentrations of IFNγ strongly upregulated PD-L1 in tumor cells in vitro, even when administered alongside high concentrations of TGFβ." (PMID 35155243, 2022). "Cetuximab engagement of CD16 activates NK cells and induces IFNγ secretion, an important soluble factor which promotes dendritic cell maturation leading to increased tumor antigen presentation and expansion of EGFR specific T cells." (PMID 36341402, 2022). "Decreased tumor-infiltrating TRegs and increased IFNγ-producing CD8+ T cells; Reprogrammed TRegs from an immunosuppressive to a stimulatory state." (PMID 35640930, 2022). "The increased PD-L1 expression, along with HLA class I and II, on tumor cells treated with Ca/N is a common theme in tumor immunotherapy and is consistent with an IFNγ driven response." (PMID 36419897, 2022). "IFNγ promoted CXCL10 secretion by myeloid cells in the tumor and, as a result, attracted more CXCR3 expressing effector T cells." (PMID 35270020, 2022). "IL12 stimulates the proliferation and cytotoxicity of CD8+ T cells and natural killer cells via the induction of cytotoxic enzymes and cytokines, mainly interferon-γ (IFNγ), to kill tumor cells." (PMID 36405748, 2022). "In the 4T1 mammary carcinoma murine model, alphavirus-mediated delivery of the IFNγ gene to the tumour significantly reduced tumour growth and induced CTL-mediated anti-tumour immune response." (PMID 36140243, 2022). "They showed that whereas inhibition of tumor IFNγ signalling led to reduced ISG expression in tumor cells, it increased ISG levels in immune cells by enhancing IFNγ production by exhausted T cells." (PMID 35251003, 2022). "IFNγ increases neoantigen presentation via MHC-I upregulation but also drives adaptive immune resistance by enhancing tumor PD-L1 expression and T-cell exhaustion." (PMID 36230753, 2022). "It is apparent that IRE produces tumor antigens that elicit an immune response, specifically via APCs that present the tumor antigens to IFNγ-expressing T cells." (PMID 35372046, 2022). "Similar to their αβ T cell counterparts, the antitumor functions of γδ T cells include direct lysis of tumor targets and secretion of inflammatory cytokines such as interferon-γ (IFNγ) that promote broader antitumor immunity." (PMID 35480230, 2022). "This discordance was mirrored by similar variation, (and statistically significant interactions), in tumour infiltration by multiple additional immune cells, and the IFNγ response—a key player in antitumour immunity and response to immune checkpoint blockade." (PMID 35262923, 2022). "In GSE37745, except for CTLA4 and IFNG, the other genes were also significantly upregulated in hot tumor group." (PMID 35211415, 2022). "According to staining for Ki67, SMAα, CD8 and Ly6G and FACS analysis, tumor remnants in anti-Ly6G-treated PtenPC−/−; Arid1aPC−/− mice exhibited reduced proliferation and stromal reactions, accompanied by increased total and IFNγ+ CD8+ T cells." (PMID 36435834, 2022). "Tumor immunosurveillance is when tumor cells are first recognized by T cells at the occurrence and growth stage, and then are killed by immune cells and secreted interferon-gamma (IFN-γ)." (PMID 35685630, 2022). "For instance, in a mouse melanoma model HIF-1α-/- CD8+ T cells show decreased expression of soluble factors including TNFα, IFNγ and granzyme B and tumor infiltration under hypoxia correlating with increased tumor growth." (PMID 35769460, 2022). "Together, these data suggest that IL-4 and IL-13 produced by ILC2s in the tumor niche promote M-MDSC-mediated suppression of anti-tumor immunity and IFNγ production, demonstrating the role of sustained innate signals in shaping the tumor microenvironment." (PMID 35658010, 2022).
tumor (continued). "A Cox proportional hazards regression analysis of the pseudo-continuous unit length-scaled IFNγ-signature scores in T1 tumours predicted a recurrence hazard ratio of 3.174 p = 0.0230." (PMID 36358715, 2022). "The function of M1 macrophages in immunity against tumors is that M1 cells are “classically activated” by IFNγ, and annihilate tumor cells via their production of nitric oxide (NO) and type 1 cytokines and chemokines." (PMID 36552048, 2022). "In patients with cancer, proinflammatory cytokines such as interleukin (IL)-1, IL-6, tumor necrosis factor alpha (TNF-α), interferon-alpha (IFN-α), and interferon-gamma (IFN-γ) are released by the tumor or the host’s immune system in reaction to the tumor." (PMID 35455957, 2022). "Reduced IFNγ expression has also been observed in NK cells pre-treated with normoxic or hypoxic tumor-derived MVs." (PMID 35031075, 2022). "Consistently, patients with high CPT score had a more favourable anti-tumour response with elevated IFNα and IFNγ response." (PMID 35999267, 2022). "On the other hand, IFNG participants in immune editing and upregulates immune checkpoints to facilitate tumor cells evade immune attacks." (PMID 35492352, 2022). "Lymphocytes are essential to host antitumor immunity through their induction of direct tumor cell cytotoxicity and cytokine secretion, such as tumor necrosis factor alpha and interferon gamma." (PMID 35242712, 2022). "Recently, T cell-derived IFNγ was found to have profound effects on the reactivation of the whole tumor microenvironment, likely including the induction of tumoricidal activity in myeloid cells." (PMID 35884605, 2022). "The IFNγ-signaturehigh basal/squamous MIBC tumours identified here appear to represent a target for immune checkpoint blockade." (PMID 36358715, 2022). "Comprehensive analysis of T cells revealed that the proportion of CD8+ tissue-resident memory T cells expressing IFNG decreased in tumor samples with advanced N stage." (PMID 35515000, 2022). "For these reasons, CD40 can turn upside down the immune suppression and drive anti-tumor as its blockade induce the secretion of IFNγ and a tumoricidal phenotype as demonstrated in preclinical models of pancreatic cancer and patients with cancer." (PMID 35664746, 2022). "IFNγ and PD-L1 signaling pathways and interactions have been studied in immune and tumor cells, but less is known about their role in other settings." (PMID 36334035, 2022). "A decrease in tumor size in three patients and raised whole blood IFNγ production after combination therapy was observed." (PMID 36686835, 2022). "Another in vitro study of CAR-NK cells targeting SLAMF7 cell therapy demonstrated an enhanced interferon-gamma production and cytotoxic activity against primary MM tumor cells, as well as inhibition of MM tumor growth in a xenograft mouse model." (PMID 35877215, 2022). "With regard to this mechanism, increasing IFNγ levels in the tumor microenvironment appears to be a promising approach to remodel susceptibility of cancer cells to ferroptosis." (PMID 35531466, 2022). "Cytotoxic enzymes can mediate direct killing of tumor cells, while production of IFNγ from NK cells as well as CD4+ and CD8+ T cells inhibits tumor growth." (PMID 35432319, 2022). "Activated NKs lyse tumor cells and stimulates the immune response via cross-talk with dendritic cells (DCs), and macrophages, via IFNγ, chemokines, and cytokines." (PMID 36432658, 2022). "We believe that IRE treatment induces IFNγ expression, which then modulates immune checkpoint molecules and thus leads to tumor recurrence." (PMID 35372046, 2022). "Further mechanistic studies showed that activation of the IFNγ and TNFα signaling pathways was significantly increased in tumor cells treated with inosine." (PMID 35488243, 2022).
tumor (continued). "In the tumor microenvironment, IFNγ can induce tumor cells to express PD-L1 and PD-L2, which subsequently interact with their receptor PD-1 on immune cells, inducing apoptosis of PD-1 positive immune cells, leading to immune suppression and evasion." (PMID 36525420, 2022). "In contrast, genetic aberrations that suppress IFNγ signaling are detected in patients relapsing from immune checkpoint blockade demonstrating that tumor-intrinsic IFNγ signaling is a clinically relevant mechanism of immune evasion." (PMID 35902886, 2022). "Tumor recognition was measured by degranulation (CD107a expression) and cytokine production (IFNγ) using flow cytometry." (PMID 35433456, 2022). "Currently, the interest is directed to further explore changes in tumour microenvironment that can be induced by IFNγ and also to investigate the combination of IFNγ with other types of immunotherapies and especially with anti-PD1 treatment." (PMID 36686827, 2022). "This analysis revealed that the expression of both the complex as a whole and each of the single components correlates with a tumor-intrinsic IFNγ response." (PMID 35395848, 2022). "The remodeling of TME by the local combination therapy elicited a systemic anti-tumor response, supported by the increased numbers of tumor cell-specific T cells in TdLNs capable of producing IFNγ upon re-encounter with cancer cells." (PMID 35780226, 2022). "M1 macrophages are classically activated by interferon-gamma (IFNγ) and lipopolysaccharides and present anti-tumor activity induced by nitric oxide synthase and release of cytotoxic reactive oxygen species and pro-inflammatory cytokines." (PMID 35740462, 2022). "Tumor-infiltrating CD8+ T cells from aPD-1 single-treated mice showed an increase of IFNγ, TNFα, and Granzyme B expression compared to untreated controls." (PMID 34423375, 2022). "Adoptive transfer experiments further confirmed that ILC2-derived IL-13 promotes immunosuppressive tumor M-MDSCs and reduces IFNγ+ T cells." (PMID 35658010, 2022). "A significant enhancement of tumor-specific IFNγ production was observed by restimulation with growth-arrested tumor cells of splenocytes isolated from murine pancreatic DT6606 subcutaneous tumors treated with a novel oncolytic Vaccinia virus." (PMID 35197076, 2022). "It seems that macrophages need several signals, such as IFNs and TLR signaling, to kill tumor cells, as illustrated with Lipopolysaccharides (LPS)/IFNγ-activated macrophages." (PMID 35884605, 2022). "NK cells are also a primary source of IFNγ, a cytokine that is critical for combating tumor growth and infection with intracellular pathogens." (PMID 36106449, 2022). "During the effector phase, activated T-cells are trafficked to specific sites by following a chemokine gradient; on contact with tumor cells, they release interferon gamma (IFN-γ) and other cytokines, promoting cytotoxicity." (PMID 35406412, 2022). "IFNG can regulate innate and adaptive immune responses, and increasing evidence has identified that IFNG can enhance antigen presentation, T-lymphocyte differentiation, and maturation to activate the tumor immune response." (PMID 35799789, 2022). "Recent efforts have aimed to uncouple MHC-I expression from interferon signalling to increase MHC-I expression in tumours with defective IFNγ signalling." (PMID 35343573, 2022). "NK cell-derived IFNγ is critical for a robust anti-tumor response as it has anti-proliferative, pro-apoptotic, and anti-angiogenic effects that inhibit tumor cell growth and regulate immune cell differentiation, activation, and homeostasis." (PMID 36498937, 2022). "On the other side, hypoxia and IFNγ synergistically work to fully activate macrophages infiltrating hypoxic tumor regions, via HIF1α and IFN regulatory factor-1 (IRF-1) interaction." (PMID 35251003, 2022). "We suspected the importance of IFNγ by performing a kinetic experiment during which fresh tumor slices were exposed for different times to EGFR CAR T cells." (PMID 36189315, 2022).
tumor (continued). "Knocking out PRDM1, which suppressed PPAR-γ co-activator (PGC) 1α, which upregulates antioxidant enzymes, increased mitochondrial mass and IFNγ production of tumor-infiltrating T cells exposed to chronic hypoxic stimulation ex vivo." (PMID 35414042, 2022). "STAT1β lacks most of the transactivation domain of STAT1 and mice expressing STAT1β exhibit defects in IFNγ signaling and decreased NK cell-dependent anti-tumor activity." (PMID 35269659, 2022). "The levels of IFNγ, TNFα, IL-5, and IL-6 were significantly higher in the mice with tumors than in the tumor-free mice." (PMID 35223517, 2022). "Better outcomes with TILs indicate that they have an anti-tumour effect and reduce growth through the release of specific cytokines, e.g., interferon-gamma, which promotes inflammation and tumour elimination." (PMID 35805770, 2022). "Compared with naïve splenocytes, vaccinated splenocytes produced dramatically greater level of IFNγ, especially when they were co-cultured with Myc inhibited B16 tumor cells." (PMID 36341364, 2022). "Addition of CXB to ICB and CTX was accompanied by diminished accumulation of intratumoral neutrophils and monocytes, and an increase in the fraction of tumor-infiltrating IFNγ-producing CD4+ and CD8+ T cells." (PMID 35440553, 2022). "We show here that in tumor : T cell co-cultures and in patients, increased IFNγ-R complex expression correlates with a stronger IFNγ response." (PMID 35395848, 2022). "These lymphocytes exert their action on tumor cells by secreting cytotoxic molecules, such as granzyme B, perforin or IFNγ, to maintain antitumor immunity." (PMID 36429101, 2022). "The prominence of IFNγ was confirmed through the aptitude of neutralizing antibodies to abolish the anti-tumor impacts of anti-CTLA-4 wholly." (PMID 35392976, 2022). "IFNγ is known to upregulate ICAM-1 expression on tumor cells by triggering a signaling pathway dependent on the phosphorylation of STAT-1." (PMID 35681548, 2022). "DNA methylation by DNA methyltransferases (DNMTs) and demethylation by ten–eleven translocation family of protein 2 (TET2) can also regulate the IFNγ signaling pathway in tumor cells." (PMID 34385592, 2022). "It seems that the local intra-tumor IFNγ production by tumor-infiltrated NK, CD4 Th1, and CD8 cytotoxic T lymphocytes together with TNFα supported the generation of high levels of specific antitumor CTLs leading to tumor growth suppression." (PMID 35736195, 2022). "Utilizing the immune deficient NSG mice enabled investigations to maintain experiments on the human cell lines investigated in vitro as well as focus on the direct effects of IFNγ upon the tumor cells." (PMID 35459800, 2022). "We separated the treated tumors into two groups based on their CD4 IFNγ expression levels and compared their tumor weights." (PMID 35651802, 2022). "These lymphocytes interact with the tumor cells via secreting IFNγ, and the tumor cells express PD‐L1 in turn to deactivate the lymphocytes and escape immune reactions." (PMID 34042312, 2022). "Bulk tumor tissue RNA-seq analysis revealed that BAY-I treatment led to significantly increased IFNγ, T-cell receptor and cytokine-cytokine receptor signaling pathways." (PMID 35013322, 2022). "Tumor areas showing higher levels of PIM exhibited minimum staining of IFNγ and CD8 signals, while the tumor areas showing lower levels of PIM were enriched with IFNγ and CD8 signals." (PMID 35840558, 2022). "Together these data suggest that the production of IFNγ by NK cells in early-stage tumors is driven by B16-ova tumor cells." (PMID 36531040, 2022). "AIM2 is induced by interferon-gamma and plays a crucial role in human solid tumors as a tumor suppressor gene." (PMID 36072791, 2022). "The respective resistance mechanism involves the upregulation of indoleamine 2,3-dioxygenase and its interaction with IFNγ, leading to the promotion of tumor immunosuppression through regulatory T-cell-dependent recruitment of myeloid-derived suppressor cells." (PMID 36291815, 2022).